ACE (angiotensin I converting enzyme)
Diseases named in the same sentence as ACE in open-access papers (continued):
Sharing a sentence is not in itself a finding about the gene and the disease.
Hypertension (continued). "The search for alternative therapies to manage arterial hypertension, particularly those based on natural products with angiotensin-converting enzyme (ACE) inhibitory activity, remains a pressing research priority." (PMID 40805672, 2025). "The development of hypertension is related to the conversion of angiotensin I into angiotensin II via the ACE system." (PMID 39942094, 2025). "Both ACE inhibitors and ARBs are widely used in clinical practice to manage hypertension, chronic kidney disease, and heart failure." (PMID 41154607, 2025). "The angiotensin-converting enzyme (ACE), a target of modern medications for the treatment of arterial hypertension, is naturally inhibited by other flavonoids such as kaempferol and apigenin." (PMID 40559631, 2025). "The ACE is a key enzyme involved in the renin-angiotensin-aldosterone system involved in pathophysiology of many diseases such as arterial hypertension, heart failure, and even cancer." (PMID 40893793, 2025). "The RAS influences cardiovascular and renal health, with angiotensin-converting enzyme (ACE) inhibitors and angiotensin II receptor blockers (ARBs) reducing hypertension and inflammation." (PMID 40727700, 2025). "The unquestionable reason for the involvement of the RAS in the pathogenesis of hypertension is the effective treatment with ACE inhibitors and angiotensin receptor blockers (ARBs), which act through the inhibition of RAS." (PMID 40149592, 2025). "We aimed to investigate the association between single nucleotide polymorphisms (SNPs) in the angiotensin-converting enzyme (ACE) gene and hypertension in elderly Japanese individuals." (PMID 40370871, 2025). "Lisinopril (LIS) is an angiotensin-converting enzyme (ACE) inhibitor that has received approval from the FDA for the treatment of hypertension and heart failure." (PMID 40940396, 2025). "Among these factors, RAAS has been extensively targeted as hypertension management medication with Angiotensin Converting Enzyme (ACE) inhibitors and Angiotensin Receptor Blockers (ARBs)." (PMID 40465783, 2025). "The link between lead exposure and hypertension is that lead can increase the level of Ang II by increasing the activity of angiotensin converting enzyme (ACE), which in turn leads to increased blood pressure." (PMID 41450520, 2025). "Angiotensin I-converting enzyme (ACE) plays a central role in blood pressure regulation, and ACE inhibitors are important in managing hypertension." (PMID 41515425, 2025). "Natural ACE inhibitors are popular in hypertension research, including L. edodes, G. lucidum, and Agaricus bisporus." (PMID 39997416, 2025). "Hypertension is manageable with ACE inhibitors or calcium-channel blockers, whereas proteinuria, thrombo-embolism, and bleeding demand closer scrutiny, especially in combination regimens incorporating anticoagulants." (PMID 41227318, 2025). "Hypertension is often treated with synthetic drugs that inhibit angiotensin-I converting enzyme; however, their action is often accompanied by unbeneficial side effects such as skin rashes, dry cough, hypotension, and angioedema." (PMID 41155415, 2025). "Angiotensin‐1‐converting enzyme (ACE) is a zinc‐dependent carboxypeptidase of therapeutic interest for the treatment of hypertension, inflammation and fibrosis." (PMID 39763019, 2025). "It should be noted that ACE inhibitors, used to treat arterial hypertension, lead to a decrease of ACE in serum and can lead to false negative findings." (PMID 40386527, 2025). "Early-stage CKD patients who present with diabetes, hypertension, substantial proteinuria, are current smokers, of Malay ethnicity, and required maximum doses of ACE inhibitor/ARB at baseline were shown to have increased odds of CKD progression." (PMID 40904355, 2025). "Beyond its effects on hypertension, ACE inhibition in rats leads to memory and learning impairments." (PMID 40281223, 2025).
Hypertension (continued). "Lisinopril, an ACE inhibitor, plays a key role in mitigating oxidative stress in dexamethasone-induced hypertension through several mechanisms." (PMID 40422564, 2025). "Of the 37 (44%) patients with hypertension, 30 were treated with angiotensin 2 receptor blockers and 7 with angiotensin converting enzyme (ACE) inhibitors." (PMID 40276567, 2025). "Angiotensin-converting enzyme (ACE) inhibitors are widely prescribed worldwide primarily for the treatment of hypertension and heart failure." (PMID 41073682, 2025). "Current CKD therapies, such as angiotensin-converting enzyme (ACE) inhibitors, angiotensin II receptor blockers, and anti-inflammatory agents, focus on controlling comorbid conditions, such as hypertension, cardiovascular disease, and diabetes." (PMID 40940724, 2025). "The drugs commonly used in the treatment of hypertension include angiotensin-converting enzyme (ACE) inhibitors, ACE receptor blockers, calcium channel blockers (CCBs), diuretics, vasodilators, beta blockers, and alpha blockers." (PMID 41480239, 2025). "In this study, we examined the effect of combined ACE inhibitor and β-blocker therapy on the prevention of cardiac death in patients with hypertension." (PMID 41134847, 2025). "Considering that ACE inhibitors are widely used for the management of hypertension, these findings require further investigation." (PMID 40281223, 2025). "The benefit of ACE inhibitors, ARBs, and statins is that they are already used routinely for the treatment of hypertension and hypercholesterolemia, and as such are easily accessible, and have a well-recognized safety profile." (PMID 40093782, 2025). "Treatments for hypertension and type 2 diabetes, including Angiotensin Converting Enzyme (ACE) inhibitors and angiotensin receptor blockers (ARBs), reduce urinary potassium excretion, which can lead to hyperkalaemia." (PMID 41228567, 2025). "RAS inhibitors, ARB, and ACE inhibitors are prioritized therapies to prevent the development of CKD with proteinuria in patients with hypertension (Kidney Disease: Improving Global Outcomes Blood Pressure Work, G. KDIGO, 2021)." (PMID 40131218, 2025). "In this regard, angiotensin-I-converting enzyme (ACE1) inhibitors are first-line pharmacological agents for hypertension." (PMID 41154073, 2025). "Ramipril (Altace) is an ACE inhibitor–type medication used to treat high blood pressure and heart failure." (PMID 39895626, 2025). "Clinically, ACE inhibitors are often used in conjunction with medications such as eprosartan, losartan, and other angiotensin II antagonists to manage hypertension and cardiovascular disorders." (PMID 41000601, 2025). "A study was conducted on Malay male individuals (72 healthy individuals and 72 newly diagnosed hypertension individuals) to assess the response to ACE inhibitors (enalapril and lisinopril)." (PMID 40342617, 2025). "Renin converts angiotensinogen to angiotensin I, and angiotensin-converting enzyme (ACE) metabolizes angiotensin I to angiotensin II, which causes high blood pressure and leads to myocardial hypertrophy and fibrosis." (PMID 41426862, 2025). "➢ Cardiovascular and anti-inflammatory agents: Drugs like quinapril (an ACE inhibitor) are used for hypertension treatment, while others are being studied for anti-inflammatory and analgesic properties." (PMID 41357103, 2025). "The peptides extracted from bonito fish demonstrate ACE inhibitory properties, which have the potential for use in treating high blood pressure." (PMID 41234609, 2025). "Bioactive peptides can inhibit the ACE activity and prevent the formation of angiotensin II from angiotensin I. This action can decrease vasoconstriction and regulate high blood pressure." (PMID 41374022, 2025). "Tailored interventions and personalized medicine hold immense promise in hypertension management, particularly in accurately predicting ACE inhibitor-induced angioedema." (PMID 38543146, 2024).
Hypertension (continued). "Hypertension is the leading cause of CVD, and ACE is an essential enzyme involved in the renin–angiotensin–aldosterone system (RAAS), which regulates blood pressure and electrolyte balance." (PMID 39061898, 2024). "The patient had a 10-year history of hypertension, controlled with oral ACE inhibitors, and a 20-year history of diabetes, managed with insulin." (PMID 39777334, 2024). "It was observed that hypertension led to an upregulation in the ACE gene expression in the KB group (p < 0.001), while ACE 2 and Mas gene expressions were inhibited (p < 0.001)." (PMID 38472752, 2024). "The role of ACE2 in SARS-CoV-2 infection arose doubts regarding the opportunity to discontinue treatments with ACE inhibitors or Angiotensin II receptor blockers, key in the treatment of hypertension, heart failure, and diabetes." (PMID 38666806, 2024). "Angiotensin-converting enzyme inhibitors (ACE inhibitors) and angiotensin II receptor blockers (ARBs) are helpful for hypertension treatment and for the prevention of left ventricular remodeling after MI." (PMID 39728296, 2024). "In the T1D group 70 of the 105 subjects with hypertension used angiotensin‐converting enzyme (ACE) inhibitors." (PMID 38124483, 2024). "Up to 35% of women had hypertension, dyslipidemia, and diabetes mellitus at baseline and up to 22% were on cardioprotective medications including ACE-inhibitors, ARBs, or beta-blockers." (PMID 38225669, 2024). "Various anti-hypertensive drugs, such as beta-blockers, diuretics, angiotensin-converting enzyme (ACE) inhibitors, angiotensin II (Ang II) receptor blockers, and calcium-channel blockers, have been developed to treat hypertension." (PMID 39125672, 2024). "Medications that block each step of the RAAS mechanism, including renin inhibitors, ACE inhibitors, and Ang II type 1 receptor antagonists, are currently used in the treatment of hypertension." (PMID 39125672, 2024). "ACE cleaves angiotensin I into angiotensin II, a potent vasoconstrictor that is a significant factor in hypertension." (PMID 38352804, 2024). "In this case study, we report the case of a 48-year-old Indian male who experienced severe plaque psoriasis flare-ups after initiating ACE inhibitor therapy for hypertension." (PMID 39364528, 2024). "Adults aged 18 years who were newly diagnosed with hypertension and received ACE inhibitors, ARBs, or thiazide diuretics as first-line antihypertensive medications were included." (PMID 38365637, 2024). "Participants on cardiac medications, such as ACE inhibitors (37.8%) and beta-blockers (26.7%), were more likely to have had previous comorbidities such as gestational diabetes and hypertension." (PMID 39850157, 2024). "Captopril, the first oral ACE inhibitor commercially applied for the treatment of hypertension, showed an IC50 value of 0.006 ± 0.000 mg mL−1." (PMID 38257227, 2024). "The ADA advocates for a target BP of less than 140/90 mmHg in T1DM patients with hypertension, with ACE inhibitors and ARBs demonstrating efficacy in reducing the risk of cardiovascular events and nephropathy in this population." (PMID 38882982, 2024). "It is proposed that one of the most important treatment strategies for managing hypertension is ACE inhibition." (PMID 39421675, 2024). "The anti-hypertension mechanism of the agent was related with dual bioactivities of ACE inhibition and antioxidant involving NADPH oxidase and Keap1/Nrf2 signaling pathways." (PMID 38933890, 2024). "Angiotensin-converting enzyme (ACE) plays a significant role in the development of hypertension in the body." (PMID 39015542, 2024). "Angiotensin-converting enzyme (ACE), a zinc dipeptide carboxypeptidase, is a key target in the pathogenesis of hypertension." (PMID 38611371, 2024). "For this reason, ACE inhibitors with antioxidant activity are widely used in hypertension treatments." (PMID 38914602, 2024).
Hypertension (continued). "Enalapril, an ACE inhibitor widely used in humans for blood pressure management, was selected for testing because of its beneficial effects on hypertension, obesity, diabetes, and congestive heart failure in aged humans." (PMID 38630424, 2024). "Lisinopril belongs to a class of medications called ACE inhibitors used in the management of hypertension, heart failure, and diabetic nephropathy." (PMID 39624172, 2024). "For patients with diabetes and hypertension, either an ACE inhibitor or angiotensin receptor blocker is recommended." (PMID 39851792, 2024). "Studies in applied models of hypertension and atherosclerosis have shown that aronia consumption leads to a reduction in ACE activity, which correlates with a systemic reduction in inflammation and improvement in vascular function." (PMID 39859963, 2024). "Research indicates that GABA derived from plant proteins such as beans, soybeans, and lentils exhibits high ACE inhibitor activity and has positive effects on hypertension." (PMID 39123629, 2024). "Ramipril is a well-known angiotensin-converting enzyme (ACE) inhibitor adapted for clinical application in the treatment of hypertension since the late 1980s." (PMID 37060536, 2024). "Regarding his medical history, the patient had a known history of arterial hypertension and dyslipidemia, both managed with tailored pharmacological therapy, including an angiotensin-converting enzyme (ACE) inhibitor and a statin." (PMID 39811230, 2024). "ACE inhibitors are used for the prevention of hypertension, cardiovascular diseases, and congestive heart failure." (PMID 38257227, 2024). "After a clinical follow-up and hypertension retargeting, the patient was discharged with dual antiplatelet therapy and ACE inhibitor drugs." (PMID 39685764, 2024). "The combined effects of vasoconstriction and fluid retention contribute to the overall elevation of blood pressure, emphasizing the central role of ACE in the pathophysiology of hypertension." (PMID 39046229, 2024). "Offspring hypertension in this model is linked to Ang II-dependent hypertension, with augmented renal ACE activity and AGT and ACE mRNA expression in adult progeny." (PMID 38542273, 2024). "The peel extracts also demonstrated in vitro inhibition on ACE, pancreatic lipase, α-glucosidase and xanthine oxidase, suggesting its potential to control hyperglycemia, detrimental weight gain, hypertension and ROS production." (PMID 38256745, 2024). "This study contributes to a deeper understanding of the mechanism of action of ACE-inhibitory peptides and bears important significance for drug development in hypertension." (PMID 39684732, 2024). "We aimed to compare the schizophrenia risk in large claims-based US and Korea cohort of patients with hypertension using angiotensin-converting enzyme (ACE) inhibitors versus those using angiotensin receptor blockers (ARBs) or thiazide diuretics." (PMID 38365637, 2024). "Significant independent predictors of severe CXR infiltrates include hypertension (OR 7.71), PTX3 (OR 1.20), and ACE D/D polymorphism (OR 18.72)." (PMID 39062191, 2024). "The first involves the variants rs1800764 and rs4291, which are thought to increase ACE expression in serum, thereby increasing arterial hypertension." (PMID 39766777, 2024). "ACE is a hydrolase of N = 598 residues acting in the blood pressure-regulating renin-angiotensin system and is a major drug target against hypertension and heart failure." (PMID 39585988, 2024). "Hypertension is often treated with medications that inhibit the renin-angiotensin signaling cascade, including angiotensin-converting enzyme inhibitors (ACE-i) or angiotensin receptor blockers (ARB)." (PMID 38281923, 2024). "ACE inhibitors and ARBs are widely prescribed for the management of hypertension, ischaemic heart disease and heart failure, which are significant factors contributing to cardiovascular morbidity and mortality in people with kidney disease." (PMID 40034484, 2024).
Hypertension (continued). "Metformin and statins had the highest consumption levels across both treatment groups followed by drugs used to treat hypertension (ACE inhibitors, aspirin and angiotensin 2 blockers)." (PMID 39439317, 2024). "ACE inhibitors are commonly prescribed medications for the management of hypertension and heart failure." (PMID 39061898, 2024). "Due to ACE’s pivotal role in hypertension, ACE inhibitors have become a mainstay in managing high blood pressure." (PMID 39452857, 2024). "Based on the current calculations, molecular docking and binding affinity provide importance to these compounds to inhibit ACE as well as to develop new therapeutics for hypertension and cardiovascular diseases." (PMID 39771606, 2024). "Extracting more efficient and safer ACE inhibitors from natural food ingredients has promising prospects for the treatment of hypertension." (PMID 38472752, 2024). "Effective treatment of hypertension can be achieved by focusing on angiotensin-I-converting enzyme (ACE), an enzyme that can be targeted." (PMID 39703330, 2024). "Current guidelines recommend five main drug classes for the treatment of hypertension: angiotensin converting enzyme (ACE) inhibitors, angiotensin receptor blockers (ARBs), β-blockers, calcium channel blockers (CCBs), and diuretics." (PMID 39592923, 2024). "Targeting the RAAS system, more specifically the ACE-Ang II-AT1R pathway has been a therapeutic strategy for hypertension, along with preventing heart and kidney damage." (PMID 38576704, 2024). "Antihypertensive medications, such as angiotensin-converting enzyme (ACE) inhibitors and angiotensin II receptor blockers (ARBs), are often used to control hypertension and reduce the strain on blood vessels." (PMID 38396849, 2024). "Based on ongoing clinical evidence, we favor the use of ARBs over ACE-Is when indicated in the management of hypertension and renal disease, more so in patients who are intolerant to ACE inhibitors." (PMID 39624172, 2024). "Supportive care includes medications such as ACE inhibitors and calcium channel blockers to reduce proteinuria and control hypertension." (PMID 39398663, 2024). "The first-line treatments for hypertension consist of beta-blockers, angiotensin-converting enzyme (ACE) inhibitors, angiotensin II receptor blockers (ARBs), loop and thiazide diuretics, and dihydropyridine calcium channel blockers (CCBs)." (PMID 39330868, 2024). "Participants in the middle tertile were less likely to have hypertension and use angiotensin-converting enzyme (ACE) inhibitors and angiotensin receptor blockers (ARB), compared to the other 2 tertiles." (PMID 38299345, 2024). "The most significant predictors of death in the regression analysis were hypertension (OR 14.0), diabetes (OR 3.87), PTX3 (OR 1.57), and ACE D/D polymorphism (OR 2.96)." (PMID 39062191, 2024). "Thiazide diuretics and CCBs are generally more efficacious than ACE inhibitors in managing hypertension." (PMID 39100000, 2024). "Apart from the obvious discrepancy in the prevalence of arterial hypertension, patients with previous ACE inhibitor treatment were older (73.8 ± 12.6 vs. 77.1 ± 11.2; p = 0.008) and more commonly of the male sex (73.2% vs. 60.5%; p = 0.011)." (PMID 39200732, 2024). "All patients were receiving treatment for chronic kidney disease, diabetes, and hypertension, including angiotensin-converting enzyme (ACE) inhibitors and angiotensin receptor blockers (ARBs) as needed." (PMID 39456691, 2024). "Activity of serum ACE (Angiotensin I Converting Enzyme), a crucial enzyme in the process of hypertension, and angiotensin II levels were significantly lower in the treated rats." (PMID 38746941, 2024). "Several studies have examined the extent of the influence of the ACE genotype on the effectiveness of ACE inhibitors in various conditions, such as hypertension, diabetic nephropathy and coronary artery disease." (PMID 38707445, 2024).